PNLIP (pancreatic lipase)
Diseases named in the same sentence as PNLIP in open-access papers (continued):
Sharing a sentence is not in itself a finding about the gene and the disease.
Obesity (continued). "Thus, the identification of phytocomponents, or bioactive molecules, from plants provides a framework and an opportunity for the development of pancreatic lipase inhibitors that could eventually be developed into anti-obesity drugs." (PMID 39328713, 2024). "In the 3T3-L1 preadipocyte cells, enhanced inhibition of pancreatic lipase was observed when emodin was combined with apigenin and naringenin, further demonstrating that emodin (80 μM) may act as a synergistic agent for the prevention of obesity." (PMID 38027005, 2023). "Focusing on appetite, pancreatic lipase activity, thermogenesis, lipid metabolism, lipolysis and adipogenesis, apoptosis in adipocytes, and adipocyte life cycle by medicinal plants and phytochemicals represent an important goal in the development of new anti-obesity drugs." (PMID 37626701, 2023). "They concluded that the anti-obesity actions of K. scoparia extract in mice fed a high-fat diet might be partly mediated through delaying the intestinal absorption of dietary fat by inhibiting pancreatic lipase activity." (PMID 37436646, 2023). "Decreasing energy intake and the intestinal absorption of dietary fats by inhibiting pancreatic lipase together with the antioxidative and anti-inflammatory effects of the different constituents of PE have been proposed as mechanisms involved in the anti-atherogenic and anti-obesity effects of PE." (PMID 36358496, 2022). "Therefore, this study examined whether HB has preventive effects on obesity by inhibiting pancreatic lipase activity and the modulation effect on the gut microbiota in HFD-fed obese-induced mice." (PMID 35897908, 2022). "Therefore, pancreatic lipase inhibitors such as saponins and phenolic compounds might be introduced as therapeutic targets in controlling obesity." (PMID 34094022, 2021). "Despite the fact that the orlistat (ORST) mechanism of action is through gastric/pancreatic lipase inhibition and its direct effect on adipocytes is equivocal, we have employed it as reference drug as it is approved and widely prescribed in anti-obesity therapeutic regimens." (PMID 33371201, 2020). "In addition, the Fraxinus plants and their isolates could be effective against obesity by decreasing fat absorption and accumulation through inhibition of pancreatic lipase." (PMID 32326102, 2020). "The present investigation was designed to evaluate antioxidant and pancreatic lipase inhibitory potential, along with identification of phyto-constituents of hydroethanolic leaf extracts of T. officinale to provide scientific evidence regarding its traditional use for obesity management." (PMID 33114490, 2020). "Out of these six plant species, O. indicum which contained baicalein showed the highest pancreatic lipase inhibitory activity and lowest lipid accumulation in 3T3-L1 adipocyte culture, indicating the great potential of this plant to be developed as herbs against obesity." (PMID 33276419, 2020). "Therefore, the inhibition of pancreatic lipase activity may prevent the occurrence of obesity as well and glucose metabolism disorders." (PMID 32471271, 2020). "Furthermore, it is also crucial to determine the effect GMF on pancreatic lipase activity as the inhibition of its activity may reduce fat absorption, and possess beneficial effects on obesity." (PMID 31791316, 2019). "Also the findings from a previous study have shown that rats fed high-fat diets containing pomegranate leaf extract exhibited decreased obesity through inhibition of pancreatic lipase, which suppressed lipid digestion and absorption, thus decreasing BW and weight gain." (PMID 30744351, 2019). "Therefore, the present study evaluated fruits of 20 different cultivars of peach for their bioactive compounds (phenolic compounds and carotenoids), antioxidant capacities, potential to inhibit enzymes relevant to hyperglycemia (α-amylase, α-glucosidase) and obesity (pancreatic lipase) management." (PMID 30284108, 2018).
Obesity (continued). "In addition, the results of another study suggested that the 46,000 Da chitosan was more effective than chitosan of 21,000 or 13,0000 Da in anti-obesity function by inhibiting pancreatic lipase activity (in vitro) and plasma triacylglycerol elevation in the oral lipid tolerance test." (PMID 28480147, 2017). "Moreover, we investigated whether hen egg yolk anti-lipase IgY inhibits pancreatic lipase activity in vitro, and examined its ability to prevent obesity in a murine high fat diet-induced obesity model." (PMID 24321125, 2013). "Thus, in this study, we investigated whether hen egg yolk anti-lipase IgY inhibits pancreatic lipase activity in vitro, and examined its ability to prevent obesity in a murine high fat diet-induced obesity model." (PMID 24321125, 2013). "The anti-obesity effects of chikusetsusaponins isolated from P. japonicus rhizomes in mice fed a high-fat diet may be partly mediated through delaying the intestinal absorption of dietary fat by inhibiting pancreatic lipase activity." (PMID 15811191, 2005). "This extract also exhibits health properties, as it has an inhibitory effect on pancreatic lipase activity, with an IC50 lower than that of Quillaja and Tribulus extracts, suggesting a potential application in anti-obesity and hypocholesterolemic therapies." (PMID 38254575, 2024). "Ellagic acid exerts anti-obesity effects through multiple mechanisms, including inhibition of adipogenesis (PPARG gene), de novo lipogenesis, and pancreatic lipase activity." (PMID 39409084, 2024). "Antidiabetic and anti-obesity potential were evaluated by inhibition of alpha-glucosidase (α-GLU), advance glycation end products (AGEs) formation and pancreatic lipase." (PMID 37508324, 2023). "The protein -protein interaction network analysis showed that PNLIP and FTO genes were identified as candidate genestargeting obesity." (PMID 37808366, 2023). "Consequently, inhibiting pancreatic lipase might be a significant way to control obesity." (PMID 37754397, 2023). "This may occur 1) when triglycerides found in chylomicrons are hydrolyzed by pancreatic lipase, leading to the production of free fatty acids and induction of free radical damage or 2) through an indirect mechanism related to atypical antipsychotics, obesity, and insulin resistance." (PMID 38044938, 2023). "Controlling the response of carbohydrate hydrolysing enzymes (α-glycosidase and α-amylase) and pancreatic lipase is an effective approach in treating post-prandial hyperglycaemia and fats metabolism in patients affected by TD2 and obesity." (PMID 37850338, 2023). "Hence, modulating human pancreatic lipase may represent an effective way to combat obesity." (PMID 35956860, 2022). "Pancreatic lipase is considered a key enzyme responsible for TG absorption in the small intestine, and the inhibition of this enzyme could be a key approach for controlling hyperlipidemia and obesity through suppression and delay of digestion and absorption of TG." (PMID 31527433, 2019). "Anti-obesity properties were studied using adipogenic differentiation inhibition of a murine mesenchymal stem cell line (C3H10T1/2) and a pancreatic lipase inhibition assay." (PMID 31861265, 2019). "The derivative of this compound has also been identified in Atractylodes lancea, a Chinese traditional herbal medicine showing pancreatic lipase inhibitory activity and a moderate anti-obesity efficacy in HFD-induced obesity mice." (PMID 29971000, 2018). "Orlistat, an inhibitor of PNLIP isolated from the bacterium Streptomyces toxytricini, was the first FDA-approved anti-obesity drug." (PMID 29538343, 2018). "In the Korean context, most of the anti-obesity agents including appetite suppressants, selective CB1 receptor blocker, and pancreatic lipase inhibitor are prescription drugs." (PMID 29902214, 2018).
Obesity (continued). "Orlistat, a classical gastrointestinal fat blocker for obesity management, was approved by the FDA in 1999 as the first lipase inhibitor to block pancreatic lipase, thereby decreasing TG digestion." (PMID 26891902, 2016). "Currently only orlistat (Xenical), a drug which is considered to be acting through inhibition of pancreatic lipase enzyme, a key enzyme for the digestion of dietary triglycerides, has been approved by FDA and is available for long-term treatment of obesity." (PMID 26640503, 2015). "However, a specific pancreatic lipase inhibitor, Orlistat, has been used in clinics for the prevention of obesity, and Orlistat has been shown not only to prevent body weight gain but also to improve obesity-induced metabolic disorders, such as glucose intolerance and diabetes." (PMID 24321125, 2013). "Other strategies for treating obesity and DM involve using drugs that act on target molecules, such as dipeptidyl peptidase IV, tyrosine phosphatase 1B, AMP-activated protein kinase, interleukin 6, chemokine ligand 2, and pancreatic lipase." (PMID 37058011, 2023). "In order to explore the potential antiarthritic and anti-obesity properties, extracts and their fractions were evaluated for their anti-denaturation effects, with the use of the BSA assay, and for their ability to inhibit pancreatic lipase." (PMID 36615228, 2022). "The pancreatic lipase is a potential pharmacological target to control obesity and does not involved complex mechanism of operation." (PMID 33114490, 2020). "Moreover, the ethyl acetate fraction proved to be effective in inhibiting pancreatic lipase, an enzyme that plays a pivotal role in the gastrointestinal digestion of dietary fat, suggesting that this species could potentially be a promising source of useful compounds for the treatment of obesity." (PMID 31936818, 2020). "In addition, pancreatic lipase and ACE are also therapeutic targets in the treatment of obesity and hypertension, respectively." (PMID 30274353, 2018). "Here, we investigated the potential anti-obesity and anti-hypertensive effects of DHSGT using a high-fat diet-induced mouse model and in vitro assays to evaluate possible DHSGT inhibition of pancreatic lipase and angiotensin-1-converting enzyme (ACE) activities." (PMID 25280587, 2014). "As a natural bioactive ingredient, saponin has been widely reported as a potential natural inhibitor of pancreatic lipase, which inhibits lipase activity and suppresses the process of fat digestion and absorption to alleviate obesity through mechanisms such as competition or noncompetition." (PMID 38794751, 2024). "Moreover, soyasaponins did not inhibit pancreatic lipase in vitro, indicating that pancreatic lipase inhibition is not always involved in the anti-obesity effect of bioactive foods." (PMID 34771142, 2021). "However, (and although lipase inhibitory activity has been studied in LAB strains) the inhibition of pancreatic lipase has not been considered as a potential mechanism of action of fermented milks with anti-obesity properties." (PMID 32775223, 2020). "Besides, pancreatic lipase inhibition does not alter any central mechanism which makes it an ideal approach for obesity treatment." (PMID 30026782, 2018). "In this study, the fat- and cholesterol-binding capacities and the inhibition of pancreatic lipase by water-soluble chitosan (WSC) with different weight-average molecular weight (Mw) were tested and compared in vitro, in order to determine the anti-obesity effects of WSC and the influence of its Mw." (PMID 28480147, 2017). "It is possible that anti-obesity effects of GBR, which might account, at least partially resulted from suppressing dietary fat digestion via inhibition of pancreatic lipase activity with subsequent excretion of the undigested fat, which was consistent with the findings of the in vitro experiment." (PMID 27216718, 2016).
Obesity (continued). "This study investigated anti-obesity effects of seven different solvent (n-hexane, toluene, dicholoromethane, ethyl acetate, absolute methanol, 80% methanol and deionized water) extracts of germinated brown rice (GBR) on pancreatic lipase activity, adipogenesis and lipolysis in 3T3-L1 adipocytes." (PMID 25367070, 2014). "In the present study, the discrepancy between anti-obesity action and inhibitory action of pancreatic lipase by orlistat could not sufficiently be clarified; therefore, this discrepancy is needed to clarify in future studies." (PMID 15811191, 2005).
pancreatitis (41 papers, 2006 to 2025). Inflammation of the pancreas. "Serum pancreatic lipase immunoreactivity (PLI) is widely recognized as a diagnostic method for canine pancreatitis." (PMID 40012749, 2025). "Pancreatitis is caused by the breakdown of triglycerides by pancreatic lipase into FFA, which become toxic to the pancreas." (PMID 38903770, 2024). "Diagnosing pancreatitis in dogs is based on the integration of serum canine-specific pancreatic lipase (cPLI) concentration, clinical presentation, and diagnostic imaging findings." (PMID 37505833, 2023). "Serum feline pancreatic lipase immunoreactivity (fPL) commonly is used in the assessment of sick cats suspected to have pancreatitis but its diagnostic utility is debated." (PMID 32452547, 2020). "Severe hypertriglyceridemia-induced pancreatitis develops as a result of increased FFA levels that are produced from triglyceride hydrolysis by pancreatic lipase and insulin deficiency." (PMID 26904318, 2016). "Feline pancreatic lipase immunoreactivity was analysed at every recheck in our study, as some case reports have suggested that exenatide may increase the risk of pancreatitis in humans." (PMID 27136422, 2016). "We performed immunohistochemical staining on those two cases and six control cases to examine whether there was detectable presence of pancreatic lipase and trypsin in the skin discolorations and whether it could be used as a feasible method to verify skin signs associated with pancreatitis." (PMID 34191249, 2021). "In one study elevated serum canine pancreatic lipase immunoreactivity (cPLI) concentration was detected in some dogs, but further diagnostic tests and clinical evaluation was not performed; thus, it is unknown if the dogs had developed clinical pancreatitis." (PMID 27206489, 2016). "Medical records of 146 dogs diagnosed with pancreatitis (serum canine pancreatic lipase ≥400 μg/L and clinical signs) were reviewed." (PMID 41333729, 2025). "The present case was also presumed to have pancreatitis based on abdominal ultrasonographic findings and the feline pancreatic lipase value of the peritoneal fluid." (PMID 39144080, 2024). "One theory is that large concentration of free fatty acids are generated through hydrolysis of triglycerides by pancreatic lipase which in turn induce pancreatitis." (PMID 38799544, 2024). "The metabolic stress engendered by acute pancreatitis, coupled with pancreatic lipase secretion during pancreatitis, can hasten fat mobilization." (PMID 38708354, 2024). "Changes in amylase activity tend to parallel the pancreatic lipase activity in dogs with pancreatitis." (PMID 37624816, 2023). "Pancreatitis is described in a study of B. rossi-infected dogs in which 28% of admitted dogs had a canine pancreatic lipase immunoreactivity level (cPLI) in the range diagnosis for pancreatitis." (PMID 38133320, 2023). "The colorimetric catalytic assay based on the use of 1,2-o-dilauryl-rac-glycero-3-glutaric acid-(6′-methylresorufin) (DGGR) ester as a substrate for pancreatic lipase activity is commonly used for the diagnosis of pancreatitis in dogs and cats." (PMID 34827904, 2021). "Specific canine pancreatic lipase (Spec cPL) measurement is considered the most sensitive and specific noninvasive test for the diagnosis of pancreatitis." (PMID 33146921, 2020). "The episodes of pancreatitis consisted of periodic acute periumbilical abdominal pain, vomiting, nausea, as well as a transient increase in enzymatic levels of amylase and pancreatic lipase." (PMID 28196530, 2017). "Canine-specific pancreatic lipase and trypsin-like immunoreactivity concentrations ruled out an underlying pancreatitis or exocrine pancreatic insufficiency, respectively." (PMID 40711264, 2025). "We next looked for evidence of PNLIP-mediated fat necrosis exacerbating cardiac injury in two previous well-established, published models of pancreatitis in obese and lean mice, i.e., cerulein pancreatitis and IL12,18-induced pancreatitis." (PMID 40460832, 2025).